EN1 (engrailed homeobox 1)
Diseases named in the same sentence as EN1 in open-access papers (continued):
Sharing a sentence is not in itself a finding about the gene and the disease.
scleroderma (1 paper, 2022). Scleroderma is a rare autoimmune connective tissue disorder characterized by abnormal hardening of the skin and, sometimes, other organs. "Pathological stainings also showed that the expressions of fibrotic markers (α‐SMA, VIM, and EN1) were significantly downregulated in the skin tissues of scleroderma mice after EM organoid treatment." (PMID 35315234, 2022).
sudden infant death syndrome (1 paper, 2018). Unexpected death in infancy which remains unexplained following autopsy, review of the medical history, and investigation of the death circumstances and death scene. "Given that abnormal development of pontine nuclei and mutations in En1 have been observed in several sudden infant death syndrome (SIDS) cases, we hypothesize that hypoxia-mediated respiratory suppression concomitant with immature responses to hypercapnia might be a major risk factor for SIDS." (PMID 29972353, 2018).
α-synucleinopathy (1 paper, 2024). "Our data show that the En1/SYN model exhibits progressive development of α-synucleinopathy accompanied by progressive loss of dopaminergic neurons that together lead to the development of motor deficits." (PMID 39187209, 2024). "In this study, we determined that the En1/SYN model displays progressive α-synucleinopathy, which was expected after the first report of the synergistic effects of inducing α-synucleinopathy in the absence of one En1 allele." (PMID 39187209, 2024). "However, the En1+/− mouse does not develop a progressive α-synucleinopathy." (PMID 39187209, 2024).
tumor (27 papers, 2009 to 2024). "In humans, aberrant EN1 expression is associated with the pathogenesis of many types of tumours, including breast cancer, prostate cancer, colorectal cancer, glioma, and nasopharyngeal carcinoma." (PMID 38291456, 2024). "Inter-Duct 3–4 cells were regulated by the TFs, MYB and EN1, and underwent activation of tumor-associated pathways." (PMID 36465348, 2022). "Consistent with our transcriptome analysis, in situ expression analysis of BRCA1-associated tumours showed significantly greater EN1 expression variability (p = 6.7 × 10−04)." (PMID 34287743, 2021). "In addition to that, EN1 can activate formation and maturation of new blood vessels, with its consequent higher risk of tumour dissemination." (PMID 35267409, 2022). "EN1 showed the most significant difference in expression between tumour and normal tissues (P<0.0001)." (PMID 38291456, 2024). "We investigated the expression of EN1 in SACC tissues and cells, EN1 promoter methylation, and the role of EN1 in tumour progression in SACC." (PMID 38291456, 2024). "As our results showed that EN1 is highly expressed in SACC tumours, we investigated the mechanism of EN1 upregulation." (PMID 38291456, 2024). "In 93 of the 100 cases, nuclear staining for EN1 was found in cells throughout the tumour, from the inner luminal cells to the outer myoepithelial cells." (PMID 38291456, 2024). "In accordance with the data from murine mT‐2D cells, EN1 overexpression increased clonogenic growth and anchorage‐independent tumor sphere formation in CFPAC1 and PaTu 8988s cells." (PMID 38110836, 2024). "Genes upregulated in EN1 are related to angiogenesis and blood vessel morphogenesis in tumor metastasis." (PMID 38328306, 2023). "In another study, high expression of EN1 correlates with short OS and increased risk of developing brain metastasis in TNBC patients due to the expression and dependency of these tumours for neural survival factors." (PMID 35267409, 2022). "Comparing with the different cluster, more malignant cells were found in Inter-Duct 3, which activated tumor-associated signaling pathways by upstream TFs, MYB and EN1." (PMID 36465348, 2022). "Inter-Duct 3–4 cells were coregulated by the upstream TFs, MYB, and EN1, which were enriched for tumor progression pathways." (PMID 36465348, 2022). "To further understand the effect of EN1 on cellular senescence in vivo, we established the lotus tumour model." (PMID 36196630, 2022). "MYB and EN1, as upstream TFs, regulated downstream genes related to domain neural activity together, histone deacetylation, and other tumor processes in Inter-Duct 3–4 cells." (PMID 36465348, 2022). "Homeobox protein engrailed-1(EN1), a homeodomain-containing transcription factor, plays a vital role in embryonic development and tumor progress." (PMID 36527158, 2022). "MC analysis appeared as the most efficient method to detect EN1 methylation in stool DNA with a sensitivity of 44% (8 out of 18) and 27% (8 out of 30) considering patients with methylated tumours or all patients, respectively." (PMID 19384295, 2009). "These EN1-iPeps have been shown to elicit a strong apoptotic response in tumor cells that overexpress EN1, effectively halting cancer cell survival without causing toxicity to normal cells that do not express EN1." (PMID 39795861, 2024). "EN1 is well known as a transcription factor in other tumours, but its role in NPC is unclear." (PMID 36196630, 2022). "Finally, to study the roles of EN1 in tumor formation in vivo, we transplanted EN1 KD and control U251 cells intracranially into nude mice and found that reducing the EN1 level significantly prolonged the survival of tumor-bearing mice." (PMID 35163043, 2022). "In addition, cytoplasmic or secreted EN1 has been previously reported as a tumor progression marker, while most of its function in tumor development is exercised by repressing or activating the expression of genes in the nucleus." (PMID 35163043, 2022).
tumor (continued). "EN1 plays a major role in development and upon deregulation in neoplasia." (PMID 19384295, 2009). "One tumor‐derived organoids (1 out of 4) from KPEC mice that we tested harbored unrecombined alleles of En1, suggesting that there might be a selective advantage for the unrecombined allele of En1 during PDA progression of a certain KPEC mice." (PMID 38110836, 2024). "The engrailed homeobox 1 (EN1)–BRD4S axis has been identified as oncogenic, while BRD4L exhibits tumor-suppressive properties, highlighting the context-dependent roles of these long and short isoforms." (PMID 37509171, 2023). "EN1 is selectively overexpressed in TNBC tumours, either basal-like BCs or quintuple negative BCs (ER-, PR-, HER2-, Cytokeratin 5/6 (CK5/6) and EGFR-)." (PMID 35267409, 2022). "The expression of EN1 and EYA4 in LGGs was prevalent among some known tumor types." (PMID 35535221, 2022). "The qMSP results confirmed significant hypomethylation of EN1 in SACC tissues compared with paired normal tissues (R2 = 0.9644), with a statistically significant difference in the overall methylation level between the tumour and normal tissues (median PMR, 0.34 vs. 0.56, P = 0.0027)." (PMID 38291456, 2024). "In addition, the lack of evidence for a field effect for most of the studied DNA regions, including for regions with frequent hypermethylation in the cancer tissue (e.g., RFX1 and EN1), is consistent with a field effect rather than contamination of adjacent samples with tumor tissue." (PMID 26510686, 2015). "Therefore, En1-Cre;mTmG mice would allow for in vivo tracing of GFP-positive CD26+ NFs and tdTomato-positive CD26− NFs during tumor development independent of changes in gene expression." (PMID 36635273, 2023).
cancer (24 papers, 2009 to 2025). A tumor composed of atypical neoplastic, often pleomorphic cells that invade other tissues. "In this work we specifically refer to EN1, a key homoeobox gene, in which aberrant DNA methylation is associated with perturbed gene expression and cancer." (PMID 33135722, 2020). "Despite this gene playing a vital role during embryonic development, EN1 has been associated with the development of cancer later in life, through changes to the methylation patterns within the gene promoter." (PMID 33135722, 2020). "Thus, these genes are important to ageing and the methylation of the EN1 gene promoter offers a potential biomarker for prediction of age-associated conditions, and in particular cancer." (PMID 33135722, 2020). "There are many developmental genes which could be investigated for their predictive capabilities, however due to its strong association with cancer, the engrailed-1 (EN1) gene is an excellent candidate." (PMID 33135722, 2020). "Cancer patients with high EN1 expression experience the lowest relapse-free survival rate, indicating the existence of an association between high EN1 expression and resistance to conventional cancer treatment such as chemotherapy." (PMID 29854286, 2018). "EN1 has been reported as a potential biomarker that correlates with the progression of a variety of human cancers." (PMID 38291456, 2024). "For example, the neural-specific transcription factor, Engrailed 1 (EN1), is exclusively overexpressed in extremely aggressive cancers." (PMID 39795918, 2024). "A prime example is the neural-specific transcription factor Engrailed 1 (EN1), which is overexpressed in particularly aggressive cancers." (PMID 39795861, 2024). "The selective nature of these peptides is a critical advantage, as they specifically target cancer cells with high EN1 expression while sparing normal cells." (PMID 39795861, 2024). "This knowledge has been used to propose the inhibition of EN1 function as a potential strategy for containing cancer cell proliferation." (PMID 39795918, 2024). "The most common epigenetic changes in cancer include promoter-specific DNA hypermethylation and gene silencing, as the downregulation of the EN1 homeobox gene observed in various cancers." (PMID 32283668, 2020). "This evidence provides a clear link between DNA methylation and subsequent perturbation of EN1 expression and cancer pathogenesis, with health in females of post-reproductive age." (PMID 33135722, 2020). "Coefficients of Cox regression were examined by data mining among 13 cancer types using OncoLnc to validate EN1 expressions in LGG patients from The Cancer Genome Atlas database (TCGA)." (PMID 31576231, 2019). "The results showed that EN1 expression in LGG was ranked statistically first among 13 different cancer types according to FDR correction." (PMID 31576231, 2019). "EN1 expression in LGG was ranked statistically first among all 13 different cancer types according to the FDR correction." (PMID 31576231, 2019). "When we compared EN1 expression among pan-cancer samples, we confirmed the highest expression of EN1 in BLBC tumors compared to all other tumors." (PMID 30349062, 2018). "Notably, EN1 has been shown to play a critical role in promoting cancer cell survival and resistance to treatment." (PMID 39795861, 2024). "As epithelial-mesenchymal transition (EMT) contributes to cancer invasion, we hypothesized that the increased migration and invasion abilities of SACC induced by EN1 may be associated with the acquisition of an EMT state." (PMID 38291456, 2024). "Experimental studies have demonstrated that knockdown of EN1 triggers potent and selective apoptosis in cancer cells, while overexpression of EN1 in normal cells leads to the activation of survival pathways, thereby conferring resistance to standard chemotherapeutic agents." (PMID 39795861, 2024). "Abnormal methylation of EN1 has been reported in many malignant tumours." (PMID 38291456, 2024).
cancer (continued). "In addition, a subset of these genes has been associated with cancer therapy responses (AZU1, CDCA3, CEACAM6, EN1, PF4)." (PMID 35008420, 2022). "The DMRs identified when comparing LowHR HRpos-like samples and TNBCs included cancer-relevant genes such as EN1, TFF3 or IRX1 which have previously been described to be differentially methylated and expressed in TNBCs and hormone receptor positive breast cancers." (PMID 34602069, 2021). "EN1 may promote the proliferation, migration and multinucleation of cancer cells via transcriptional activation of HDAC8, UTP11L and ZIC3." (PMID 31576231, 2019). "Additionally, the basal-like cell line HCC-1569 showed the highest expression of EN1 among all cancer cells." (PMID 30349062, 2018). "Similarly, expression of BLAT1 and EN1 are significantly correlated in pan-cancer samples (p < 0.001)." (PMID 30349062, 2018). "The high prevalence of methylation in EN1 CpG island (three out of every four carcinomas show hypermethylation of this gene) together with its possible functional role in cancer lead us to evaluate its putative clinical usefulness as a diagnostic marker of disease." (PMID 19384295, 2009). "Their research indicated that some epigenetic drivers, like regulatory regions of ABCC1 and VEGFA, appeared in pan-cancer, while some epigenetic regulators, like FGF19, ASAP2 and EN1, and the PBX3 motif, are cancer specific." (PMID 40041484, 2025). "Some epigenetic drivers appeared in multiple cancers (for example, regulatory regions of ABCC1 and VEGFA; GATA6 and FOX-family motifs), whereas others were cancer specific (for example, regulatory regions of FGF19, ASAP2 and EN1, and the PBX3 motif)." (PMID 37914932, 2023). "We chose CDKN2A and RASSF1 since hypermethylation of these genes has been widely reported in a variety of cancers including NSCLC, and the EN1 promoter region since hypermethylation of EN1 had been previously reported in a lung tumor cell line but not yet in primary NSCLC tumors." (PMID 22726460, 2012).
infection (2 papers, 2011 to 2012). The state of being infected such as from the introduction of a foreign agent such as serum, vaccine, antigenic substance or organism. "During Neural Stage II at 32 dpi (right-hand panels), the proportion of EN1+ cells increased approximately four-fold in lenti-MEF2CA—infected cells compared to control infection." (PMID 21901155, 2011). "However, at 1 day post-infection, Egr1 and En1 were identified as enriched transcription factor binding sites in genes downregulated in WT mice, but not KO mice." (PMID 22713837, 2012). "We found that infection with lenti-MEF2CA significantly increased the expression of these DA neuron-related genes and the proportion of anti-EN1/TH—labeled neurons." (PMID 21901155, 2011).
head and neck tumours (1 paper, 2022). "Subsequently, validation of EN1 using the TCGA‐HNSC database revealed that it was also highly expressed in head and neck tumours." (PMID 36196630, 2022).
EN1 also shares sentences with these, for which no sentence is quoted: prostate carcinoma (4 papers); cerebellar ataxia (2); Mowat-Wilson syndrome (2); ovarian carcinoma (2); salivary gland adenoid cystic carcinoma (2); adenocarcinoma (1); ampullary carcinoma (1); bacterial infection (1); bladder cancer (1); cleidocranial dysplasia (1); colorectal adenoma (1); colorectal tumours (1); cousin syndrome (1); dysplasia (1); Dystonia (1); Endove syndrome (1); Fuhrmann syndrome (1); intraductal papillary mucinous neoplasms (1); knee osteoarthritis (1); Lesch-Nyhan disease (1); leukemia (1); microphthalmia (1); neurodegenerative disease (1); neurofibroma (1); oligoastrocytoma (1); oligodendroglioma (1); ovarian tumor (1); papillary thyroid carcinoma (1); Phocomelia (1); Sagittal craniosynostosis (1).
A further 2 diseases each share a sentence with EN1 in 1 paper.